IL6 (interleukin 6)
Diseases named in the same sentence as IL6 in open-access papers (continued):
Sharing a sentence is not in itself a finding about the gene and the disease.
pulmonary fibrosis (continued). "Similar studies in pulmonary fibrosis, analyzed peripheral blood gene expression, identifying transcripts associated with disease severity; including the activation of STAT3 by IL-6 in progressive fibrosis." (PMID 36388923, 2022). "Treatment of idiopathic pulmonary fibrosis (IPF) fibroblasts with IL-6, on the other hand, conferred resistance to FasL-induced apoptosis." (PMID 36147459, 2022). "The mice then develop skin and lung fibrosis with a defined Th2/Th17 response and increased IL-6 production." (PMID 36726987, 2022). "Together with reactive oxygen species, IL-6, IL-8, IL-1β, GM-CSF, and other chemokines cause ARDS, leading to pulmonary fibrosis and death." (PMID 34463916, 2022). "IL-6 boosts lung fibrosis by not only activating pulmonary fibroblasts but also promoting M2 macrophage polarization." (PMID 36299447, 2022). "IL-6, an alcohol-induced inflammatory response-related gene, is closely related to the occurrence of some diseases such as pulmonary fibrosis, breast neoplasms, and postmenopausal osteoporosis." (PMID 36230124, 2022). "The release of proinflammatory cytokines like TNF-α, IL-1β, and IL-6 in the lung tissue microenvironment by stimulated macrophages and fibroblasts contributes to the persistence of lung fibrosis by activating fibroblasts in an autocrine/paracrine fashion." (PMID 35377906, 2022). "In the SSc animal model, BAFF contributed to the skin and lung fibrosis by increasing IL-6-producing effector B-cells and suppressing IL-10-producing regulatory B-cells." (PMID 36590969, 2022). "It is also reported that quercetin and gallic acid restore lung SOD and GSH levels while decreasing the inflammation factors, NO, and IL-6 levels in BLM-induced pulmonary fibrosis in rats." (PMID 38059201, 2022). "The occurrence of an SS-like condition with pulmonary fibrosis and skin thickening was determined by IL-6 signaling." (PMID 35203527, 2022). "Other recently published data point to the same increased level of IL-6 in cases of SS with advanced pulmonary fibrosis due to the perpetuation of chronic inflammation, inhibition of the secretion of metalloproteinases, and increased collagen fiber synthesis." (PMID 35203527, 2022). "The transcription of many inflammatory cytokines, such as TNFα, IL6, IL1β and TGFβ, are vital in development of lung fibrosis." (PMID 35083615, 2022). "Treatment with SDC2 protected mice from the development of bleomycin-induced lung fibrosis in the inflammatory arthritis mouse model and tended to decrease bronchoalveolar fluid levels of IL-6." (PMID 35181688, 2022). "Skin and lung fibrosis was abrogated by administration of neutralizing antibodies against IL-6 or IL-23." (PMID 34854378, 2021). "We also found that transferred CD45−/ALDHbr cells ameliorated BLM-induced pulmonary fibrosis by suppressing IL-6 and TGF-β." (PMID 34425896, 2021). "A previous study in vivo also showed induction of STAT3-mediated Gremlin-1 in lung fibrosis and a recent paper demonstrated that IL-6 trans signaling in idiopathic pulmonary fibroblasts elevated Gremlin-1, which was reduced with tocilizumab." (PMID 34150776, 2021). "Many studies have reported a relationship between IL-6 and the involvement of internal organs, especially lung fibrosis." (PMID 34064515, 2021). "Studies have observed that fibroblasts induce fibroblasts to transform into myofibroblasts by secreting IL-6, which promotes the occurrence and development of pulmonary fibrosis." (PMID 35069217, 2021). "Some authors suggested that specifically IL-6 is the key cytokine leading to inflammatory storm phenomena increasing alveolar-capillary blood-gas exchange dysfunction, pulmonary fibrosis, and organ failure." (PMID 34360706, 2021). "Of note, serum IL-31 levels positively correlated with the severity of skin and lung fibrosis and serum levels of IL-4, IL-6, and IL-13, which suggests the association of IL-31 with fibrosis and Th2 immune responses in SSc." (PMID 34642338, 2021).
pulmonary fibrosis (continued). "Recent evidence indicates that JAK inhibitors or monoclonal antibodies directed to block IL-6 are used as compassionate use to attenuate the excessive inflammation and lung fibrosis related to SARS-CoV-2 virus." (PMID 34207510, 2021). "For instance, IL-6 blockade using an IL-6-neutralizing antibody in the early or late phase of BLM-induced pulmonary fibrosis resulted in the exacerbation or amelioration of pulmonary fibrosis, respectively." (PMID 34530920, 2021). "Another study using IL-6 gene silencing showed that, in induced lung fibrosis, IL-6 played an important role in the regulation of the expression of Th2 cytokines (IL-4 and IL-5)." (PMID 34941770, 2021). "We previously found that SERCA2a overexpression inhibits IL6/STAT3 signaling in vivo using the bleomycin-induced pulmonary fibrosis model and in vitro in pulmonary fibroblast isolated from healthy donors." (PMID 34502015, 2021). "Prophylactic treatment with KB004 but not KB243 over 35 days completely prevented the development of lung fibrosis and increased IL-6 expression." (PMID 33945505, 2021). "Various investigations have revealed that Thal prevents bleomycin- or paraquat-induced pulmonary fibrosis in murine models by downregulating the expression of IL-6, IL-8, IL-1β, TNF- α, TGF-β, collagen, hydroxyproline, VEGF, p-JNK and α-SMA." (PMID 35126133, 2021). "Previous studies have demonstrated that significantly increased expressions of IL-1β, IL-8 and IL-6 in bronchoalveolar lavage fluid from patients with pulmonary fibrosis in comparison with controls." (PMID 34742261, 2021). "Blocking IL-6 at this stage accelerates pulmonary fibrosis, possibly by enhancing apoptosis of ATIIs54." (PMID 33723241, 2021). "IL-4, IL-6 and IL-17 also contribute to pulmonary fibrosis by promoting collagen synthesis and transdifferentiation of fibroblasts to myofibroblasts." (PMID 34876129, 2021). "SF-MSCs inhibited the reduction in serum transforming growth factor-β1 and the increase of interleukin-6 in both the serum and the bronchoalveolar lavage fluid during bleomycin-induced pulmonary fibrosis." (PMID 34530920, 2021). "In fact, when KB004 treatment was implemented earlier, i.e., from days 7 to 35, reduced lung fibrosis and IL-6 expression were observed." (PMID 33945505, 2021). "A recent paper with IPF shows that Spp1 is primarily expressed in myeloid cells in interstitial pulmonary fibrosis and IL-6 stimulates OPN expression in macrophages, which sensitizes and mobilizes fibroblasts toward other fibrogenic growth factors." (PMID 34830342, 2021). "This early fibrosis was attenuated by LXA4 as was the expression of proteins involved in pulmonary fibrosis, including IL-6, TGF-β, α-SMA, and Twist." (PMID 32811815, 2020). "This study highlighted the high complexity of the IL-6 signaling by identifying for the first time the dual anti/pro-fibrosis role of IL-6 in the pathogenesis of lung fibrosis." (PMID 32587955, 2020). "MP infection can lead to the increase in pro-inflammatory cytokines, TNF-α and chemokine, such as IL-6 and promotes various leukocytes (mainly neutrophils) aggregation at the infection site, eventually resulting in lung injuries and pulmonary fibrosis." (PMID 32597476, 2020). "IL-6 also promotes pulmonary fibrosis after silica exposure, with excessive extracellular matrix proliferation." (PMID 32256366, 2020). "For example, lung fibrosis-associated genes (CSF3, IL8, CSF2, IL6, TNF, MMP9, IL1B and PDGFB) were significantly upregulated in SARS-CoV-2-infected NHBE cells." (PMID 32698440, 2020). "Activation of p38 MAPK signaling pathway in pulmonary macrophages promotes lung fibrosis through secretion of IL-6, IL-1β, and TNF-α, all of which are the direct targets of p38 MAPK pathway." (PMID 32271749, 2020).
pulmonary fibrosis (continued). "In both (PQ) and (BLM)-induced pulmonary fibrosis models, the core pro-inflammatory cytokines underlying the pathogenicity of these conditions such as TNF-α, IL-6, IL-1β, and TGF-β are common with that of COVID-19 cases." (PMID 32574274, 2020). "CCL12 (MCP1), which is elevated in pulmonary fibrosis, has been reported to mediate fibroblast survival through IL-6." (PMID 32969837, 2020). "Similar results were obtained in a mouse model of silica-induced lung fibrosis, where nintedanib reduced the IL-6 concentration in lung tissue." (PMID 32337244, 2020). "This deleterious impact of IL-6 on the development of lung fibrosis was analyzed in different mouse models." (PMID 31694340, 2019). "The cytokine IL-6 functions as a proinflammatory factor as well as a profibrotic factor in pulmonary fibrosis, and the signaling pathway of IL-6/Stat3 has been shown to play an important role in the pathogenesis of lung fibrosis." (PMID 31309122, 2019). "Blockade of the second increase in IL-6 by IL-6-neutralizing antibody during the fibrotic stage of BLM-induced lung injury can improve lung fibrosis." (PMID 31049028, 2019). "Recent publications have reported, though, that it is the activation of the A2B receptor by adenosine that mediates production of pro-inflammatory, pro-fibrotic molecules, like interleukin-6, leading to chronic lung diseases, particularly pulmonary fibrosis." (PMID 31379836, 2019). "Pulmonary fibrosis was attenuated in P2Y2-deficient mice via a reduction in neutrophil recruitment, migration, and proliferation of fibroblasts and interleukin 6 (IL-6) production." (PMID 31379836, 2019). "Interleukin 6 (IL-6) is an inflammatory cytokine produced by many cells and its inhibition reduces the lung fibrosis in murine model." (PMID 29854623, 2018). "Contradictorily, in idiopathic pulmonary fibrosis, trans‐signalling of IL‐6 is activated and specific disruption of it can significantly attenuate pulmonary fibrosis." (PMID 28881473, 2018). "Bleomycin-induced pulmonary fibrosis increases lung IL-6 and TNF-α levels and subsequently elevates MCP-1 levels; MCP-1 then recruits macrophages to the lung tissue." (PMID 29772024, 2018). "In our experimental model of BLM-induced lung fibrosis and PH, we report increased levels of Has2, Il-6 and Tgm2 following BLM exposure compared to PBS exposure in TaglnCre mice." (PMID 29910735, 2018). "Different studies suggest that IL-1β, IL-6, IL-8, MIP-1α, LTB4, and TGF-β1 levels are associated with subsequent BPD development and promote lung fibrosis." (PMID 29209598, 2017). "The current results agreed with researchers who found increases in TNF, IL-1β, and IL-6 in bronchoalveolar lavage fluid in pulmonary fibrosis rat model." (PMID 28883083, 2017). "This is supported by an earlier report that showed blocking IL‐6 at days 8, 9, and 10 after bleomycin instillation can ameliorate lung fibrosis." (PMID 28371562, 2017). "Here, we investigated the effect of transient adenoviral overexpression of OSM or IL-6 in mice during bleomycin-induced lung fibrosis." (PMID 29038604, 2017). "In current study, after receiving Ilomastat pretreatment combined irradiation, TGF-β and IL-6 expression significantly decreased, and the severity of alveolitis and pulmonary fibrosis reduced in our experiment." (PMID 28977826, 2017). "In this study, ANP significantly attenuated the elevated mRNA levels of MCP-1and IL-6 in BLM-induced pulmonary fibrosis." (PMID 28049526, 2017). "Our data demonstrated that PQ-induced IL-6 expression in macrophages plays a central role in pulmonary fibrosis through enhanced epithelial-to-mesenchymal transition (EMT)." (PMID 28194150, 2016). "In summary, our study reveals the role of IL-6 in PQ-induced pulmonary fibrosis and a new epigenetic mechanism that controls the transcription of IL-6 in macrophages." (PMID 28194150, 2016).
pulmonary fibrosis (continued). "IL-6 expression and its role to enhance PQ-induced pulmonary fibrosis were increased by histone deacetylase (HDAC) inhibition and prevented by histone acetyltransferase (HAT) inhibition." (PMID 28194150, 2016). "Given the previous data showing IL-6 play a vital role in pulmonary fibrosis, we next explore its regulation mechanism." (PMID 28194150, 2016). "In conclusion, IL-6 functioning through EMT in PQ-induced pulmonary fibrosis was regulated dynamically by HDAC and HAT both in vitro and in vivo via epigenetically regulating chromatin accessibility." (PMID 28194150, 2016). "Pulmonary fibrosis and fibrotic genes can be alleviated by blocked IL-6 trans-signaling with recombinant soluble gp130Fc." (PMID 28194150, 2016). "Our study shows that HDAC inhibitors promote the expression of IL-6 mRNA and protein, thus PQ-induced pulmonary fibrosis was aggravated." (PMID 28194150, 2016). "To determine the functional role of IL-6 in PQ-induced pulmonary fibrosis, we next blocked IL-6 trans-signaling with recombinant soluble gp130Fc." (PMID 28194150, 2016). "Together, our study uncovered the epigenetic regulatory mechanism of IL-6 in macrophages that played a critical role in PQ-induced pulmonary fibrosis." (PMID 28194150, 2016). "CNP reduced mRNA levels of the profibrotic cytokines interleukin (IL)-1β and IL-6, as well as collagen deposition and the fibrotic area in lungs of mice with bleomycin-induced pulmonary fibrosis." (PMID 26895702, 2016). "Overexpression of interleukin 6 (IL-6) has been proposed to contribute to pulmonary fibrosis and other fibrotic diseases." (PMID 28194150, 2016). "Together, our data demonstrated that PQ-induced IL-6 expression in macrophages plays a central role in pulmonary fibrosis through enhanced EMT transition." (PMID 28194150, 2016). "IL-6 release from macrophages in response to PQ mainly plays a central role in pulmonary fibrosis through enhanced EMT transition in pulmonary epithelial cells." (PMID 28194150, 2016). "The role of cytokines in fibrosis formation has become a hot spot of research and IL-6 has ability to promote fibrosis formation alone or together with TNF-α in bleomycin-induced pulmonary fibrosis." (PMID 28194150, 2016). "Taking these findings together, IL-6 at the early inflammatory stage of BLM-induced lung injury functions as an inhibitory factor in the epithelial injury-based mechanisms of lung fibrosis." (PMID 26289430, 2015). "In contrast, blockade of the second increase of IL-6 by IL-6-neutralizing antibody ameliorated lung fibrosis." (PMID 26289430, 2015). "Recently, besides TGF-β/Smad3 signaling, the signaling loop of IL-6/gp130/Stat3 has been shown to play a crucial role in the pathogenesis of lung fibrosis." (PMID 26289430, 2015). "IL-6 is a pleiotropic cytokine whose importance in various lung disorders including pulmonary fibrosis has been demonstrated extensively." (PMID 26369416, 2015). "Our selection includes cytokines previously associated with the lung response to radiation in both mice and humans such as Il6 and Tnfα) as well as pulmonary fibrosis-promoting Il1β, Il13 and Il17) and anti-fibrotic mediators Il10 and Ifnγ." (PMID 25889053, 2015). "Neutralization of IL-6 at the early fibrotic stage of BLM-induced lung injury significantly ameliorated lung fibrosis." (PMID 26289430, 2015). "BLM eventually effectively induces lung fibrosis, suggesting that the protective role of IL-6 as a compensatory mechanism cannot intrinsically overcome BLM-induced lung fibrosis and is masked in the final pathological outcome." (PMID 26289430, 2015). "A-MWCNTs delivered to the lungs of mice by OPA had reduced mRNA or protein levels of IL-1β, IL-6, OPN and TNF-α relative to U-MWCNT at 1 or 28 days post-exposure and A-MWCNTs caused less lung fibrosis in mice relative to U-MWCNTs." (PMID 25216247, 2014). "In this study, there was a significant reduction in bleomycin induced lung fibrosis in the IL-6-/- mouse as compared to wild type mice." (PMID 24478703, 2014).
pulmonary fibrosis (continued). "Further, the pro-fibrotic role of IL-6 and its signaling pathway was examined in vivo using the bleomycin model of lung fibrosis in an IL-6-/- mouse." (PMID 24478703, 2014). "Transcription factor STAT3 is associated with chronic inflammatory diseases and the transcription products of STAT3, such as IL-6, IL-10, and IL-17, are involved in the pathogenesis of pulmonary fibrosis." (PMID 23869224, 2013). "Because IL-6 has been linked to the development of acute interstitial pneumonia, we expected that EGFR-TKI treatment-induced IL-6 production in cancer cells resulted in lung fibrosis." (PMID 23592411, 2013). "IL-6, in addition to being a broad pro-inflammatory marker, is a target for IL-1β-induced lung fibrosis." (PMID 23741300, 2013). "In a previous study, CCL2 was reported to contribute to the development of lung fibrosis by reducing IL6 levels." (PMID 23874655, 2013). "These macrophages produce chemokines (including KC, MIP-2) and pro-inflammatory cytokines (including IL-6 and IL-1β) that recruit other inflammatory cells to the lung, culminating in pulmonary fibrosis." (PMID 22708497, 2012). "In mice model of silica-induced lung fibrosis, IL-6 and IL-23 seemed independent to the modulation of Th17 by Tregs." (PMID 22615967, 2012). "We next sought to determine if treatment with IL-6 neutralizing antibodies had an effect on the pulmonary fibrosis seen in Ada-/- mice." (PMID 21799929, 2011). "In contrast to the BP group (PN started on Day 2), IL-6 levels and pulmonary fibrosis scores were lower in the BD group." (PMID 21423633, 2011). "Collectively, these findings indicate that treatment with IL-6 neutralizing antibodies attenuates pulmonary fibrosis in Ada-/- mice." (PMID 21799929, 2011). "Elevated levels of pro-inflammatory cytokines and chemokines such as TNF, IL-6 and CXCL8 are associated with several human diseases including cystic fibrosis, pulmonary fibrosis and AIDS." (PMID 20507572, 2010). "In pre-clinical studies, Pirfenidone altered TGF-β transcription in a murine model of bleomycin-induced pulmonary fibrosis, IL-6 expression in rat models of acute pulmonary inflammation, and expression of ICAM-1 in cultured human fibroblasts." (PMID 17540023, 2007). "Oroxylin A reduced inflammatory score and bronchiolar epithelium thickness, inhibited airway construction and central airway resistance, improved pulmonary fibrosis, increased inspiratory capacity and quasi‐static compliance, and suppressed IL‐1β and IL‐6 activity levels in mice model of RP." (PMID 41509128, 2026). "The role of the IL-6/IL-17 axis is appreciated in the progression of pulmonary fibrosis." (PMID 39964756, 2025). "The results showed that pulmonary fibrosis may be mitigated following AT-MSCs transplantation in PQ-poisoned mice by suppressing the synthesis of pro-inflammatory cytokines (interleukin-6 and tumor necrosis factor-alpha) in the lung tissues of the animals." (PMID 40665395, 2025). "Interleukin 6 (IL-6) is involved in the development of pulmonary fibrosis by stimulating the expression of genes related to collagen, promoting the growth and differentiation of fibroblast and myofibroblast cells, inhibiting the apoptosis of T cells, and regulating the balance between Th17 cells." (PMID 40843700, 2025). "Of note, Il6-KO mice had decreased lung fibrosis after bleomycin lung injury." (PMID 40875483, 2025). "IL-6 is an important profibrotic factor and is a therapeutic target in clinical lung fibrosis." (PMID 40875483, 2025). "Additionally, IL-6-deficient mice have been shown to exhibit reduced macrophage and neutrophil accumulation following BLM administration, resulting in attenuated pulmonary fibrosis." (PMID 41323794, 2025).